YES1 (YES proto-oncogene 1, Src family tyrosine kinase)
Description:
Non-receptor protein tyrosine kinase that is involved in the regulation of cell growth and survival, apoptosis, cell-cell adhesion, cytoskeleton remodeling, and differentiation. Stimulation by receptor tyrosine kinases (RTKs) including EGFR, PDGFR, CSF1R and FGFR leads to recruitment of YES1 to the phosphorylated receptor, and activation and phosphorylation of downstream substrates. Upon EGFR activation, promotes the phosphorylation of PARD3 to favor epithelial tight junction assembly. Participates in the phosphorylation of specific junctional components such as CTNND1 by stimulating the FYN and FER tyrosine kinases at cell-cell contacts. Upon T-cell stimulation by CXCL12, phosphorylates collapsin response mediator protein 2/DPYSL2 and induces T-cell migration. Participates in CD95L/FASLG signaling pathway and mediates AKT-mediated cell migration. Plays a role in cell cycle progression by phosphorylating the cyclin-dependent kinase 4/CDK4 thus regulating the G1 phase. Also involved in G2/M progression and cytokinesis. Catalyzes phosphorylation of organic cation transporter OCT2 which induces its transport activity.
Synonyms: YES; c-yes; HsT441; P61-YES
Tractability: Small molecule: an approved drug acts on it; a high-quality ligand is known; it belongs to a druggable protein family. Antibody: its Gene Ontology location is reachable by antibodies, with high confidence; UniProt places it where antibodies can reach, with medium confidence; the Human Protein Atlas places it where antibodies can reach. PROTAC: it is named in the literature on targeted protein degradation; ubiquitination databases record sites on it; its protein half-life has been measured; a small molecule that binds it is known.
Target class: Kinase; TK protein kinase group; Enzyme; Protein Kinase; Tyrosine protein kinase Src family
Chemical probes: DGY-06-116 (high quality), SU6656
Gene: Protein-coding gene on chromosome 18 (721,588 to 813,276, reverse strand). Ensembl gene ENSG00000176105.
Subcellular location: Cell membrane; Cytoplasm, cytoskeleton, microtubule organizing center, centrosome; Cytoplasm, cytosol; Cell junction
Subcellular location (Human Protein Atlas): Cytosol; Plasma membrane
Pathways (Reactome):
Immune System: Co-inhibition by CTLA4; Co-stimulation by CD28; FCGR activation; Regulation of signaling by CBL; Signaling by CSF1 (M-CSF) in myeloid cells
Developmental Biology: EPH-Ephrin signaling; EPH-ephrin mediated repulsion of cells; EPHA-mediated growth cone collapse; EPHB-mediated forward signaling
Disease: FCGR3A-mediated IL10 synthesis; FCGR3A-mediated phagocytosis; Signaling by phosphorylated juxtamembrane, extracellular and kinase domain KIT mutants
Signal Transduction: Regulation of KIT signaling; Signaling by ERBB2; Signaling by SCF-KIT
Gene expression (Transcription): RUNX2 regulates osteoblast differentiation
Hemostasis: PECAM1 interactions
Gene Ontology:
Molecular function: enzyme binding; phosphotyrosine residue binding; protein binding; protein tyrosine kinase activity; transmembrane transporter binding; non-membrane spanning protein tyrosine kinase activity; signaling receptor binding; ATP binding; protein kinase activity
Biological process: cell differentiation; cell surface receptor protein tyrosine kinase signaling pathway; ephrin receptor signaling pathway; Fc-gamma receptor signaling pathway involved in phagocytosis; leukocyte migration; negative regulation of inflammatory response to antigenic stimulus; protein modification process; regulation of vascular permeability; T cell costimulation
Cellular component: cytosol; extracellular exosome; focal adhesion; Golgi apparatus; plasma membrane; anchoring junction; actin filament; centrosome
Genetic constraint (gnomAD): Loss-of-function variants: 31 observed, 55.72 expected, observed/expected ratio (o/e) 0.56, 90% interval 0.42 to 0.75. The upper end of that interval is the gene's LOEUF score, 0.75, which puts it in group 3 of 6, group 1 being the genes least tolerant of losing a copy. Missense variants: 422 observed, 548.31 expected, observed/expected ratio (o/e) 0.77, 90% interval 0.71 to 0.83. Synonymous variants: 166 observed, 188.51 expected, observed/expected ratio (o/e) 0.88, 90% interval 0.77 to 1.
Homologues: Orthologues: macaque YES1 (99% identical), chimpanzee YES1 (99% identical), dog YES1 (98% identical), guinea pig YES1 (96% identical), mouse Yes1 (96% identical), rat Yes1 (96% identical), pig YES1 (91% identical), tropical clawed frog yes1 (90% identical), zebrafish yes1 (87% identical). Paralogues in human: SRC (75% identical), FYN (74% identical), FGR (68% identical), HCK (57% identical), LYN (53% identical), LCK (52% identical), BLK (51% identical), FRK (44% identical), ABL2 (39% identical), ABL1 (38% identical), PTK6 (37% identical), SRMS (36% identical), and 20 more.
Diseases named in the same sentence as YES1 in open-access papers:
YES1 is named in the same sentence as 59 diseases in open-access papers, as found by Europe PMC text mining. Sharing a sentence is not in itself a finding about the gene and the disease. The quoted sentences say what the papers report.
breast carcinoma (15 papers, 2010 to 2026). "Src family kinase Yes1 has been associated with poor survival in HER2+ breast cancer and amplification or mutation can cause neratinib resistance." (PMID 39191139, 2024). "Only the downregulated expressions of ZFP161, PPP4R1 and YES1 were correlated with the luminal B subtype suggesting their potential involvement in the genesis of a particularly aggressive form of breast cancer with 18p loss." (PMID 20698951, 2010). "The gene amplification, overexpression, and activation of YES1 have been observed in trastuzumab-resistant HER2-positive breast cancer cells (BR-474-R) and trastuzumab/lapatinib-dual-resistant BT-474-RL2 cells." (PMID 38338729, 2024). "Relapse-free survival and disease-specific survival of patients with HER2-positive breast cancer with higher YES1 mRNA expression were significantly shorter than those of patients with lower expression." (PMID 38338729, 2024). "The inhibition of YES1 expression using shRNA has been demonstrated to impair the growth of basal-like breast cancer cell lines, including MDA-MB-468, MDA-MB-231, and BT549." (PMID 38338729, 2024). "YES1 amplification was detected in HER2-positive breast cancer BT-474 cells that had developed resistance to neratinib." (PMID 38338729, 2024). "The same finding was made in ERBB2+ trastuzumab-resistant breast cancer, in that the control of ERBB2 leads to loss of kinases such as WNK1 and YES1 implicated in this cancer mechanism of resistance." (PMID 37359373, 2023). "Targeting YES1 was effective to restore the sensitivity to chemotherapeutic drugs (trastuzumab and lapatinib) in drug-resistance breast cancer cell lines." (PMID 36386788, 2022). "Consistent with cell line data, high expression of Yes1 mRNA was correlated with worse prognosis in patients with HER2-positive breast cancer." (PMID 28158234, 2017). "To elucidate the impact of Yes1 expression on the prognosis in HER2-positive breast cancer patients, we performed bioinformatics analysis using two different cohorts." (PMID 28158234, 2017). "In the acquisition of the resistance to trastuzumab/lapatinib, there is a possibility that a switch to Yes1 was induced to breast cancer cells depending on HER2 for proliferation, as dasatinib alone had an enough power to treat the resistant cells." (PMID 28158234, 2017). "Although the poor prognostic factor is not strictly equivalent to the resistance mechanism to trastuzumab, the results from clinical data support that Yes1 has a pivotal role in HER2-positive breast cancer." (PMID 28158234, 2017). "YES1 binds to HER2 in neratinib-resistant breast cancer cells." (PMID 38338729, 2024). "Taken together, we demonstrate that by destabilizing ERBB2, we controlled and downregulated YES1 and WNK1 that are well-known causes of drug resistance in ERBB2+ trastuzumab drug-resistant breast cancer and in osimertinib-resistant EGFR T790M lung cancer, respectively." (PMID 37359373, 2023). "The possibility that YES1 might serve as a therapeutic target for breast cancer therapy as a means of overcoming drug resistance has already been reported." (PMID 34884609, 2021). "YES1 gene amplification occurs in some types of cancer and is a key mechanism of resistance to EGFR or HER2 inhibitors, while downregulation of YES1 inhibits cell growth in several malignancies, including colon carcinoma, rhabdomyosarcoma, and basal-like breast cancer." (PMID 33941853, 2021). "Higher Yes1 expression was correlated with worse prognosis in HER2-positive breast cancer patients." (PMID 28158234, 2017). "We further investigated whether overexpression of Yes1 had any impact on clinicopathological characteristics of breast cancers." (PMID 28158234, 2017). "Proto-oncogene tyrosine-protein kinase (YES1) has been widely reported to stimulate cancer cell growth and migration in various cancer types such as lung cancer, gastric cancer, and breast cancer, which is therefore considered as a novel therapeutic target for cancer therapy." (PMID 36386788, 2022).
breast carcinoma (continued). "We previously reported that YES1, a member of the Src family, plays an important role in acquired resistance to trastuzumab in HER2-amplified breast cancer cells." (PMID 34884609, 2021). "We previously established a trastuzumab-resistant breast cancer cell line (named BT-474-R) from the HER2-amplified cell line BT-474 and reported that YES1, a member of the Src family, plays an important role in acquired resistance to trastuzumab." (PMID 34884609, 2021). "In conclusion, we found that Yes1 is a key molecule for the resistance mechanism of trastuzumab and lapatinib in a certain population of HER2-positive breast cancers." (PMID 28158234, 2017). "Yes1 plays an important role in acquired resistance to trastuzumab and lapatinib in HER2-positive breast cancer." (PMID 28158234, 2017). "The ectopic expression of miR-33b downregulated the expression of ADAM9, HMGA2, LDHA, SALL4, SNAI2 and Twist1 by more than 30% but had minimal effects on HIF-1α, RAC1, Yes1 and ZEB1 in these two breast cancer cell lines." (PMID 25919570, 2015). "We also previously reported that higher YES1 expression correlated with poor outcomes for HER2-positive breast cancer patients, and the inhibition of YES1 appears to be an urgent clinical issue in breast cancer and other malignancies." (PMID 34884609, 2021).
gastric cancer (15 papers, 2017 to 2024). A primary or metastatic malignant neoplasm involving the stomach. "has-miR-140-5p is an underlying prognostic factor for gastric cancer patients, being capable of mediating YES1 (YES proto-oncogene 1 and Src family tyrosine kinase) suppression." (PMID 35310909, 2022). "For example, hsa-miR-140-5p directly targets FEN1 and YES1 in cervical and gastric cancer, respectively, thereby inhibiting cancer cell proliferation, migration, and invasion." (PMID 39684278, 2024). "We proved that YES1 was a target of miR-145-5p in gastric cancer cells using luciferase assay and biotin-labeled miR-145-5p pull-down assay." (PMID 35017464, 2022). "In conclusion, linc01133, a JUN and FOS regulated lncRNA, promoted gastric cancer cell growth as a ceRNA for miR-145-5p via YES1 mediated YAP1 nuclear translocation." (PMID 35017464, 2022). "In particular, in gastric cancer, miR-140-5p suppresses the proliferation, migration and invasion of tumour cells by regulating YES1." (PMID 33902514, 2021). "Similarly, YES1 phosphorylates ANXA2 on Tyr24, which drives gastric cancer invasion and metastasis by the activation of EphA2/YES1/ANXA2 axis." (PMID 36247003, 2022). "Several target genes of miR-140-5p have been identified, including platelet-derived growth factor receptor A (PDGFRA) in ovarian cancer, insulin-like growth factor 2 mRNA-binding protein 1 (IGF2BP1) in cervical cancer, and YES proto-oncogene 1 (YES1) in gastric cancer." (PMID 30962263, 2019). "Indeed, the expression of CDK4, CDK6 and cyclin D1, which are expressed predominantly in the G1 phase and promotes the transition to S phase of the cell cycle, closely correlated with the expression of YES1 and YAP1 in gastric cancer cells and tumor xenografts." (PMID 35017464, 2022). "Here, we show that EphA2, YES1, and ANXA2 form a signal axis, in which YES1 activated by EphA2 phosphorylates ANXA2 at Tyr24 site, leading to ANXA2 activation and increased ANXA2 nuclear distribution in gastric cancer (GC) cells." (PMID 33941853, 2021).
lung carcinoma (11 papers, 2020 to 2025). "Recent studies have shown that lung cancer with increased YES1 was more responsive to Dasatinib, and increased expression of YES1 was reported to be one of the acquired resistant mechanisms to EGFR inhibitors in lung cancer with EGFR mutations." (PMID 32923394, 2020). "In the present study, SRC and YES1 exhibited elevated expression and activation in lung tissues from both lung cancer patients and mice exposed to radiation." (PMID 39776795, 2025). "This circRNA can regulate the proliferation, invasion, and apoptosis of lung cancer cells by sponging miR-145 or controlling miR-944/YES1 axis." (PMID 36902312, 2023). "Recent studies have highlighted the role of YES1 in lung cancer development, identifying YES1 as a potential target involved in lung cancer carcinogenesis." (PMID 35508982, 2022). "Moreover, high YES1 protein expression was an independent predictor for poor prognosis in patients with lung cancer." (PMID 38791306, 2024). "Studies have shown that the amplification of YES1 is a targetable and recurrent mechanism of resistance to EGFR inhibition in EGFR-mutant lung cancer." (PMID 39940833, 2025). "Molecular alterations of YES1, a member of the SRC, can be found in a significant subset of patients with lung cancer." (PMID 38791306, 2024). "For example, in ERBB2-overexpressing EGFR T790M lung cancer, we controlled and degraded ERBB2 and as well degraded EGFR, MET, and YES1 kinases that are known to drive this tumor resistance to drugs." (PMID 37359373, 2023).
hepatocellular carcinoma (9 papers, 2017 to 2025). A malignant tumor that arises from hepatocytes. "Selective inhibition of Yes1 kinase activity resulted in significant inhibition of HEV infection in hepatoma cells and primary human hepatocytes, as well as in a rat HEV in vivo model system." (PMID 39560373, 2024). "YES1 is expressed not only in the membrane and cytoplasm, but also in the nuclei of cancer cells in human hepatocellular carcinoma tissues and a human HCC cell line." (PMID 38338729, 2024). "The LINC00998-encoded short peptide SMIM30 can enhance the tumorigenesis of hepatocellular carcinoma through the regulation of the SRC/YES1/MAPK pathway." (PMID 37285335, 2023). "YES1 is suppressed by miRNAs in the tumor progression of oral cancer, ovarian cancer, and hepatocellular carcinoma, and this observation indicates that YES1 may be regulated by miRNAs in GC." (PMID 28818100, 2017). "RBM15 modulates m6A modification of YES proto-oncogene 1 (YES1) mRNA in an IGF2BP1-dependent manner, promoting hepatocellular carcinoma progression, indicating RBM15/IGF2BP1 regulates the m6A modification of other genes in other diseases." (PMID 40592832, 2025). "To investigate whether Yes1 affects progeny virus production, we next transfected HEV p6 full-length RNA into hepatoma cells in the presence or absence of Y1KI, followed by titration on HepG2/C3A cells." (PMID 39560373, 2024).
colon carcinoma (7 papers, 2014 to 2024). "YES1 directs this complex to the anti-apoptotic gene promoters, such as Bcl-xL and survivin, thereby promoting colon cancer cell survival." (PMID 38338729, 2024). "YES1 is a well-known proto-oncogene that participates in the growth, differentiation, and invasion of cancers, such as colon carcinoma, rhabdomyosarcoma, esophageal cancer and others." (PMID 34707107, 2021). "Among them the Src family member YES1 has been reported as a direct miR-145 target that plays oncogenic function in colon cancer, FSCN1 and PPP3CA are also directly regulated by this miRNA in esophageal squamous cell carcinoma and urothelial carcinoma." (PMID 25069957, 2014). "While both YES1 and Src can phosphorylate YAP1 at the Tyr-357 residue, only YES1 is crucial for the survival of β-catenin-active colon cancer cells." (PMID 38338729, 2024). "In the later colon cancer progression stages, elevated YES1 levels and activity promote cell motility rather than tumor growth." (PMID 38338729, 2024). "YES1 and YAP1 interact within the context of β-catenin-active colon cancer SW480 cells." (PMID 38338729, 2024). "Inhibiting the tyrosine 357 phosphorylation of YAPInhibiting interaction of YES1, YAP, and β-catenin complex independent of YES1 kinase activityInhibition of gut formation to a similar extent as the YAP or YES1 knockdownImpeding β-catenin-dependent proliferation of colon cancer cell lines." (PMID 28035075, 2017). "Moreover, clinical results indicated that the transcript levels of YES1 and YAP are higher in colon cancer patients with liver metastases after 5FU-based neoadjuvant chemotherapy, which was also positively correlated with colon cancer recurrence and shorter patient survival." (PMID 36835173, 2023).